TPO (thyroid peroxidase)
Diseases named in the same sentence as TPO in open-access papers (continued):
Sharing a sentence is not in itself a finding about the gene and the disease.
Hashimoto thyroiditis (continued). "Further analysis of the patients with Hashimoto’s thyroiditis with different TPO antibody levels showed that tumor size and concurrent nodular goiter were the risk factors in the group with normal TPO antibody levels (p < 0.05)." (PMID 40496557, 2025). "Typical findings include hypothyroid profiles (elevated TSH, low T3/T4) and raised anti‐Tg or anti‐TPO levels in Hashimoto thyroiditis." (PMID 41141239, 2025). "Lastly, we assessed anti-thyroid peroxidase (anti-TPO) antibodies, which are autoimmune markers commonly elevated in subclinical hypothyroidism and Hashimoto’s thyroiditis." (PMID 41465826, 2025). "In the analysis of patients with different Hashimoto’s thyroiditis statuses, it was found that patients with higher TPO antibody levels were younger and had higher TSH levels (p < 0.05)." (PMID 40496557, 2025). "In the present study, Hashimoto's thyroiditis patients were diagnosed according to high serum levels of anti-thyroid peroxidase antibodies (anti-TPO>50 IU/mL)." (PMID 40060227, 2025). "The clinical data showed that the clinicopathological characteristics varied in different states of Hashimoto’s thyroiditis and levels of the thyroid peroxidase (TPO) antibody (p < 0.05)." (PMID 40496557, 2025). "In particular, all subjects with anti-TTG positivity were also anti-TPO positive, highlighting a strong correlation between autoimmune hypothyroidism and celiac disease." (PMID 41280993, 2025). "Anti-TPO levels in Hashimoto's thyroiditis patients are significantly higher than in the control group (P<0.001)." (PMID 40060227, 2025). "Seven patients (15.5%), including two with Hashimoto’s thyroiditis, were positive for anti-thyroid peroxidase (TPO) and/or thyroglobulin (Tg) antibodies." (PMID 41438737, 2025). "In the reported case, the hyperthyroid phase of Hashimoto's thyroiditis (Hashitoxicosis) has been differentiated from Graves' disease based on elevated TPO antibody levels and low TSI, the latter being specific for Graves' disease." (PMID 39911620, 2025). "In patients with known disease durations (ranging from 9 months to 29 years) of Hashimoto’s thyroiditis (n = 22), the developed multiplex avidity method revealed a correlation between the avidity index of autoantibodies to TPO and disease duration." (PMID 39941271, 2025). "Patients with Hashimoto’s thyroiditis produce antibodies against various thyroid antigens, most commonly anti-thyroid peroxidase (anti-TPO) and antithyroglobulin (anti-Tg), with TSHR antibodies being less frequently detected." (PMID 40416990, 2025). "Among the 100 people in the control group, two had TSH of more than normal for their age, and their T4 and anti-thyroid peroxidase antibodies levels were also normal, suggesting subclinical non-autoimmune hypothyroidism." (PMID 39123137, 2024). "Two of the 12 women had s-anti-TPO levels above RV and were diagnosed with autoimmune hypothyroidism." (PMID 38078923, 2024). "Specifically, offspring gestated in mothers afflicted with Hashimoto’s thyroiditis with elevated thyroid peroxidase antibody (TPO-Ab+) levels were found to have approximately an 80% increased probability of developing autistic traits." (PMID 38752179, 2024). "At 7 months, she was diagnosed with type 1 diabetes mellitus (positive islet cell and glutamic acid decarboxylase antibodies) and autoimmune hypothyroidism (positive thyroid peroxidase and antithyroglobulin antibodies)." (PMID 38404237, 2024). "Hashimoto’s disease is a chronic lymphocytic thyroiditis characterized by the production of antibodies against thyroglobulin and thyroid peroxidase." (PMID 39771538, 2024). "This is not supportive of autoimmunity being directly responsible for persistent symptoms in patients with euthyroid Hashimoto disease—provided that anti-TPO antibody levels can be accepted as a proxy for general autoimmune activity." (PMID 38606313, 2024). "Thyroglobulin and thyroid peroxidase autoantibodies were positive, confirming autoimmune hypothyroidism." (PMID 39081695, 2024).
Hashimoto thyroiditis (continued). "In terms of autoimmunity, eight patients are positive to anti-TPO antibodies and two have autoimmune disorders, namely, Celiac disease, and Hashimoto thyroiditis." (PMID 39416263, 2024). "Both patients with Hashimoto’s disease and those with Graves’ disease can present high anti-TPO levels, and thus this parameter cannot be effectively applied in the differential diagnosis." (PMID 39000209, 2024). "TPO antibody as well as thyroglobulin antibody were significantly elevated at 574 IU/mL and >2,500 IU/mL, respectively, values consistent with Hashimoto's thyroiditis." (PMID 39483562, 2024). "Hashimoto’s thyroiditis (HT) is generally characterized by the presence of thyroid peroxidase and thyroglobulin antibodies, with a concomitant infiltration of lymphocytes in the thyroid." (PMID 38731922, 2024). "The anti-thyroid peroxidase antibodies (anti-TPO) were elevated, 830 IU/mL (reference: < 35 IU/mL), corroborating the diagnosis of Hashimoto’s thyroiditis, while anti-thyroglobulin antibodies and TSH receptor antibodies (TRAbs) were negative." (PMID 39816290, 2024). "This in turn causes thyroid peroxidase and other thyroid enzymes to be exposed to the immune system, resulting in a spike in thyroid peroxidase antibodies similar to Hashimoto’s disease." (PMID 39650960, 2024). "Anti-thyroid peroxidase (TPO) and thyroglobulin antibodies were elevated, confirming a diagnosis of Hashimoto’s thyroiditis." (PMID 39483562, 2024). "During the research, anti-TPO antibodies were the most frequently increased ones and statistically occurred more often in children with a positive family history of Hashimoto’s thyroiditis." (PMID 37270495, 2023). "Serum TSH, anti-TG, and anti-TPO levels were typically lower in controls and much higher in patients with Hashimoto’s thyroiditis." (PMID 37241088, 2023). "A total of 13 out of 18 patients diagnosed with Hashimoto’s thyroiditis 72.2% were found to have positive thyroid peroxidase antibody test." (PMID 36832519, 2023). "Autoantibodies such as anti-thyroglobulin antibody (TgAb) and anti-thyroid peroxidase antibody (TPOAb) are involved in the pathogenesis of chronic thyroiditis." (PMID 37731007, 2023). "Im Rahmen der Hashimoto Thyroiditis kommt es zum Auftreten von Antikörpern gegen die Thyroid-Peroxidase (TPO) oder Thyreoglobulin, sowie zu einer Erhöhung der TSH Konzentration." (PMID 37101030, 2023). "Negativation of autoantibodies against thyroglobulin and/or thyroid peroxidase was observed in four children with Hashimoto’s thyroiditis (one girl and three boys) of a total of eleven children diagnosed with Hashimoto’s." (PMID 37238410, 2023). "Serum TSH, anti-TG, and anti-TPO levels were typically lower in controls and much higher in individuals with Hashimoto’s thyroiditis." (PMID 37241088, 2023). "Thyroid peroxidase antibody (TPOAb) and thyroglobulin antibody were found to be positive in 90% of patients with Hashimoto's thyroiditis." (PMID 37190929, 2023). "In Hashimoto’s thyroiditis, 200 μg of sodium selenite or selenomethionine per day for 3 and 6 months was found to alleviate auto-TPO Ab and anti-thyroglobulin antibody titers and improve thyroid echogenicity." (PMID 37060084, 2023). "In an open controlled trial of 60 patients with chronic lymphocytic thyroiditis, the combination of L-T4+ Se possessed better efficacy than L-T4 monotherapy compared to the L-T4 group, TPO-Ab and TG-Ab were significantly reduced." (PMID 37033262, 2023). "High levels of anti-thyroid antibodies, which mainly involve thyroid peroxidase (TPO) as well as anti-thyroglobulin antibodies, are present in most people suffering from Hashimoto’s disease." (PMID 37908940, 2023). "Hashimoto’s thyroiditis is distinguished by the presence of autoantibodies against thyroid peroxidase and thyroglobulin." (PMID 36980259, 2023). "Anti-TPO antibodies were elevated more often in patients with a positive family history of AD, including Hashimoto’s thyroiditis (n = 3; p = 0.044)." (PMID 37270495, 2023).
Hashimoto thyroiditis (continued). "A total of 13 out of 18 patients diagnosed with Hashimoto’s thyroiditis (72.2%) were found to have positive thyroid peroxidase antibody test, which has been noticed that there is a rising incidence of autoimmunity in young people." (PMID 36832519, 2023). "Antibodies to thyroglobulin (IgG anti-TG) are also markers of Hashimoto’s disease, alongside IgG anti-TPO, although with a lower sensitivity and specificity." (PMID 37511088, 2023). "Serum samples from three patients with Hashimoto’s thyroiditis and anti-TPO antibody titers 21-fold, 26.3-fold and 29.6-fold the upper level of normal rapidly killed thyroid epiCsTPO in CDC assays." (PMID 36593395, 2023). "In order to rule out the influence of thyroid disease on P/T, our study screened patients with Hashimoto’s thyroiditis by TPO-Ab and ultrasonography, and further analyzed patients without thyroid disease." (PMID 37113486, 2023). "Hashimoto’s disease is diagnosed based on the clinical picture, elevated serum levels of anti-TPO and/or anti-TG antibodies, abnormal serum levels of thyroid hormones, and a characteristic ultrasound image of the thyroid gland." (PMID 35565695, 2022). "In Hashimoto’s disease, low production of vitamin D appears to be related to a higher titer of anti-TPO antibodies and to thyroid volume, and supplementation was associated with a reduction of antibodies in some studies." (PMID 35208518, 2022). "According to certain studies, the markers of worsened OxS in patients with Hashimoto thyroiditis were closely related to the levels of TG or TPO antibodies." (PMID 36686463, 2022). "Autoantibodies against thyroid peroxidase (TPO) and thyroglobulin (TG), which characterize Hashimoto’s thyroiditis (HT), and thyroid-stimulating receptors (TSHR), a marker for Graves’ disease (GD), were used in this study." (PMID 36002642, 2022). "The most diagnosed AID in our cohort was Hashimoto thyroiditis with positive anti-TPO and/or anti-Tg antibodies diagnosed by an endocrinologist, which was found in 23 (17.6%) patients." (PMID 35923829, 2022). "Anti-thyroglobulin and anti-TPO antibodies were observed in 23/79 patients (29%), but only one patient presented clinically overt autoimmune hypothyroidism." (PMID 36556267, 2022). "Among them, one patient was seropositive for anti-thyroid peroxidase autoantibody, and a diagnosis of Hashimoto's thyroiditis was subsequently made." (PMID 35463126, 2022). "In people with Hashimoto thyroiditis, anti-TPO antibodies depend on GSH levels and exhibit an inverse correlation." (PMID 36686463, 2022). "Antibodies against thyroid peroxidase and thyroglobulin are the most specific biochemical markers for lymphocytic thyroiditis." (PMID 35573548, 2022). "Some studies also reported that high anti-TPO titers appear to protect against differentiated thyroid cancer in patients with Hashimoto’s thyroiditis." (PMID 34966357, 2021). "In Hashimoto's thyroiditis, anti-TPO antibodies can be one of the autoantibodies targeting the gland." (PMID 34667679, 2021). "Antimicrosomal autoantibodies from individuals with Graves' or Hashimoto's thyroiditis were able to bind to isolated TPO and block the mAb binding to purified TPO in a dose-dependent manner." (PMID 34667679, 2021). "Hashimoto thyroiditis is characterized by T-cell mediated autoimmune response; serum concentrations of anti-TPO and anti-Tg vary the degree of thyroid hypofunction and cause intrathyroidal infiltration of B and T-cell CD4+ type 1 T helper cells." (PMID 35140907, 2021). "Unfortunately, the major antigen in human Hashimoto’s disease is thyroid peroxidase (thyroperoxidase, TPO, EC 1.11.1.1–14), an enzyme that participates in the synthesis of thyroid hormones." (PMID 34065957, 2021). "The latest meta-analysis, covering 22 studies, showed that obesity is statistically significantly correlated with Hashimoto’s disease (p = 0.022) and high levels of anti-TPO antibodies (p = 0.001)." (PMID 33808030, 2021).
Hashimoto thyroiditis (continued). "Autoallergy is also possible in patients with CSU and Hashimoto’s disease because these patients demonstrated higher levels of IgE anti-thyroid peroxidase antibodies in comparison to controls." (PMID 34906225, 2021). "Anti-TPO antibodies show a dependence on glutathione levels, demonstrating an inverse relationship in individuals with Hashimoto’s thyroiditis." (PMID 34573074, 2021). "As expected, anti-TG and anti-TPO auto-antibodies were significantly higher in the group of patients with lymphocytic thyroiditis (Group 1) (p<0.001 for both)." (PMID 35317375, 2021). "Two patients had persistent subclinical hypothyroidism with positive anti-TPO, likely pre-existing Hashimoto’s thyroiditis diagnosed upon admission for COVID-19." (PMID 34659128, 2021). "Endocrine testing revealed elevated TSH and anti-thyroid peroxidase antibodies, resulting in a diagnosis of Hashimoto’s disease." (PMID 34938854, 2021). "Of note, a pilot study showed that following a gluten-free diet for six months significantly reduced the serum titers of thyroid peroxidase antibodies and thyroglobulin antibodies in patients with Hashimoto’s thyroiditis." (PMID 34975767, 2021). "Hashimoto thyroiditis (HT) is the most common autoimmune disease worldwide, characterized by chronic inflammation and circulating autoantibodies against thyroid peroxidase and thyroglobulin." (PMID 33746942, 2021). "The major autoantigens in Hashimoto's disease are thyroid peroxidase (TPO) and thyroglobulin (Tg) antibodies, and the annual incidence of HT worldwide is estimated to be 0.3 to 1.5 cases per 1000 persons." (PMID 32256575, 2020). "In particular, its therapeutic effect has been described for Hashimoto’s thyroiditis, including reducing titers autoantibodies against thyroid peroxidase and thyroglobulin of and T helper 17 (Th17) cells." (PMID 33304319, 2020). "Our patient demonstrated cognitive impairment, encephalopathy, mood disturbances, and status epilepticus in the setting of Hashimoto’s thyroiditis with elevated anti-TPO Abs." (PMID 32923205, 2020). "Actually, several studies have reported the association between nodal metastasis and chronic lymphocytic thyroiditis (CLT), which can demonstrate an increased serum level of TPO-Ab." (PMID 33193092, 2020). "In this study, a significantly higher prevalence of Hashimoto’s thyroiditis in the form of positive TPO Ab was found in late-onset psoriasis (onset ≥ 40 years old) in comparison with early-onset psoriasis." (PMID 31157131, 2019). "Thyroid peroxidase is the major antigen in human Hashimoto’s disease, and anti-TPO antibodies induce complement-dependent cytotoxicity." (PMID 31366075, 2019). "In routine, Hashimoto's thyroiditis is diagnosed by the elevated level of anti-TPO-Ab and high level of TSH and treated with levothyroxine, and many studies have shown that the serum levels of anti-TPO-Ab decline during levothyroxine treatment." (PMID 31428301, 2019). "Anti-TPO antibodies are more common (90-95%) in Hashimoto's thyroiditis than anti-TG antibodies in Hashimoto's thyroiditis." (PMID 31428301, 2019). "Various studies reported a high occurrence (61%) of Hashimoto's thyroiditis in the form of diffuse goiter and 93 percent of these patients were anti-TPO positive." (PMID 31428301, 2019). "Thyroid antibodies against thyroglobulin (TgAb) and thyroid peroxidase (TPOAb) are key markers of Hashimoto’s thyroiditis (HT), the most common autoimmune thyroid disorder." (PMID 30926877, 2019). "Anti-TPO antibodies present in almost 90% of Hashimoto's thyroiditis which makes them the most common anti-thyroid autoantibodies, in addition around 75% of Graves' disease and 10-20% of nodular goiter or thyroid carcinoma have positive anti-TPO antibodies." (PMID 31592370, 2019). "Owing to the increased incidence of Hashimoto thyroiditis, thyroid function tests and thyroid peroxidase antibodies should also be checked in patients with idiopathic RPF." (PMID 31431986, 2019).
Hashimoto thyroiditis (continued). "Hashimoto’s thyroiditis typically occurs between the ages of 30 and 50 and is much more common in women than men, which influence the TPO Ab level." (PMID 30862792, 2019). "In a Turkish study including 80 patients and 80 control subjects, the frequency of anti-TPO antibodies and the prevalence of Hashimoto‘s thyroiditis were significantly higher among cases." (PMID 29900171, 2018). "Thyroid peroxidase (TPO) and thyroglobulin (Tg) are the major autoantigens in Hashimoto’s disease, but antibodies against those antigens (TPO-Ab and Tg-Ab) occur also in ~ 70% of patients with GD." (PMID 29931474, 2018). "For example, 10% of a disease-free population was reported to have positive results for anti-thyroid peroxidase antibodies (TPOAb) or antithyroglobulin (anti-Tg), indicating that many patients have potentially chronic lymphocytic thyroiditis." (PMID 28870235, 2017). "Autoantibodies against TPO and hashimoto's thyroiditis are detected in 10–20% of patients with CFS and lead to thyroid destruction through antibody dependent cellular cytotoxicity and complement activation." (PMID 28604802, 2017). "Hashimoto’s thyroiditis is characterized by the presence of thyroid auto-antibodies such as anti-thyroid peroxidase (TPO-Ab) and anti-thyroglobulin (TG-Ab) antibodies in the serum while these antibodies have potential ability to deteriorate thyroid cells." (PMID 27852303, 2016). "Subclinical autoimmune hypothyroidism (the presence of TPO-Abs with raised TSH and normal FT4 levels) is even more prevalent and affects about 9% of the population." (PMID 27092550, 2016). "It is therefore not surprising that in our cohort the observed effects of age, gender, smoking, and TPO antibodies on the eye signs in patients with Hashimoto's thyroiditis are similar to those reported for Graves' disease." (PMID 26798548, 2015). "Anti-TPO antibodies are the most prevalent and present in 80–90% of Hashimoto's thyroiditis, 65–75% of grave's disease, and 10–20% of nodular goiter or thyroid carcinoma." (PMID 26435714, 2015). "The extracellular antigenic part of TPO, which is known to be connected to the complement in autoimmune hypothyroidism, contains four sites for Asn N-glycosylation (aminoacid sequence: NXS/T, X different than proline)." (PMID 25003133, 2014). "Autoimmune disease is the principal etiology of hypothyroidism and particularly Hashimoto's thyroiditis with anti-thyroperoxidase antibodies (anti-TPO)." (PMID 24497920, 2014). "Increased levels of anti-TPO antibodies are usually found in about 95% and anti-TG antibodies in about 60% of the cases of autoimmune hypothyroidism, according to bibliography." (PMID 25003133, 2014). "Anti-TPO autoantibodies are found in over 90% of patients with autoimmune hypothyroidism and Graves' disease." (PMID 23878745, 2013). "Thyroglobin (TG) and TPO antibodies occur in very high concentration in patients with Hashimoto's thyroiditis and primary myxedema." (PMID 23878745, 2013). "Six of the patients with Hashimoto thyroiditis had anti-TPO, one had anti-Tg, and one had both anti-TPO and anti-Tg while 4 had alterations in thyroid function tests." (PMID 23118611, 2012). "Hashimoto’s thyroiditis was diagnosed in our case on findings of seropositivity for Tg and TPO autoantibodies, and slightly high TSH accompanied by morphological changes seen on thyroid ultrasound." (PMID 22839422, 2012). "The authors found anti-TPO autoantibodies in 40% of PV patients and 7% of the controls; only one of the patients with anti-thyroid antibodies had Hashimoto thyroiditis." (PMID 23118611, 2012). "Another Hashimoto thyroiditis patient's serum with high titers of both anti-TPO and anti-TG antibodies confirmed by radioimmunoassay was employed as positive control in indirect immunofluorescence assay." (PMID 22126669, 2011).